F11R (F11 receptor)
Diseases named in the same sentence as F11R in open-access papers (continued):
Sharing a sentence is not in itself a finding about the gene and the disease.
pancreatic cancer (12 papers, 2013 to 2025). "However, the behavioral changes in pancreatic cancer cells caused by the expression of F11R remain unclear, and the identification of F11R as a novel antipancreatic cancer target therefore holds interest." (PMID 35295710, 2022). "In conclusion, the results of this study showed that the knockdown of the F11R gene can be effectively silenced by lentiviral transfection of the pancreatic cancer cell line PANC-1 in vitro." (PMID 35295710, 2022). "To investigate the role of F11R in the carcinogenesis of pancreatic cancer and the potential targets of F11R as a therapeutic target for pancreatic cancer, we knocked down F11R in the pancreatic cancer cell line PANC-1 using lentiviral approaches." (PMID 35295710, 2022). "Through pre-experiment, we found that the F11R gene was highly expressed in five pancreatic cancer cell lines (MIA paca-2, bxpc-3, cfpac-1, SW1990, and PANC-1) and tumor specimens from 30 pancreatic cancer patients (data not shown)." (PMID 35295710, 2022). "Then, it was found that the knockdown of F11R revealed that the growth of the pancreatic cancer cell line PANC-1 was inhibited by CCK-8 assays." (PMID 35295710, 2022). "The knockdown of F11R can inhibit cell proliferation and colony formation, promote apoptosis, and inhibit metastasis in pancreatic cancer cell lines PANC-1." (PMID 35295710, 2022). "The results indicated that the knockdown of the F11R gene arrested the pancreatic cancer cell cycle in the G1 phase." (PMID 35295710, 2022). "In order to explore the role of F11R in pancreatic cancer, we knockdown the F11R gene of the PANC-1 cell line with F11R-shRNA lentivirus." (PMID 35295710, 2022). "F11R/JAM-A depletion in pancreatic cancer tissue specimens related to poor overall patient survival calculated by the Kaplan–Meier method." (PMID 34533648, 2022). "Numerous studies have shown that the aberrant expression of F11R contributes to tumor progression including pancreatic cancer." (PMID 35295710, 2022). "The results showed that the migration ability of pancreatic cancer cells in the F11R-KD group knocking down the F11R gene was significantly decreased, indicating that silencing the F11R gene can effectively inhibit the metastatic ability of pancreatic cancer cells." (PMID 35295710, 2022). "In order to investigate whether the F11R gene affects the metastatic ability of pancreatic cancer cells, the transwell assay was carried out." (PMID 35295710, 2022). "Therefore, we further explored the effects of the F11R gene on the malignant biological behavior of pancreatic cancer cells by knocking down the F11R gene and establishing a negative control group, laying a foundation for future molecular pathway research." (PMID 35295710, 2022). "Therefore, we speculate that the expression of F11R is related to the malignant biological behaviors of pancreatic cancer." (PMID 35295710, 2022). "However, the significance of F11R in various tumors is controversial, and the role of F11R in regulating the malignant behaviors of human pancreatic cancer is unknown." (PMID 35295710, 2022). "The present results suggest that F11R may be a promising therapeutic target for pancreatic cancer." (PMID 35295710, 2022). "This suggests that the F11R gene may play a role as oncogene in pancreatic cancer cell lines." (PMID 35295710, 2022).
reovirus infection (10 papers, 2012 to 2025). "Furthermore, it was proven that F11R/JAM-A is involved in the development of several pathologies, such as cardiovascular diseases, inflammatory bowel disease, rheumatoid arthritis, neurological disorders, reovirus infection, and various cancer types." (PMID 34533648, 2022).
breast tumor (9 papers, 2011 to 2023). "The F11R/JAM-A overexpression in breast tumor tissue was associated with aggressive cancer phenotypes." (PMID 37563645, 2023). "Another investigation elucidated that a specific anti-F11R/JAM-A monoclonal antibody reduced murine breast tumor xenograft growth." (PMID 34533648, 2022). "Junctional adhesion molecule A or F11R being an important junctional adhesion molecule is known to play a vital role in cell migration, invasion and adhesion contributing to carcinogenesis and has been reported to be over-expressed in kidney, lung, and breast tumor tissues." (PMID 35642021, 2022). "In vivo murine studies have confirmed the F11R/JAM-A role in apoptosis and breast tumor proliferation." (PMID 34533648, 2022). "In 2008, the first published evidence indicated that in breast tumor metastases, F11R/JAM-A expression is decreased versus in normal human mammary epithelium." (PMID 34533648, 2022).
glioma (9 papers, 2013 to 2024). A benign or malignant brain and spinal cord tumor that arises from glial cells (astrocytes, oligodendrocytes, ependymal cells). "In the female tumor microenvironment, F11R inhibits pathogenic microglial activation and indicates sex differences in glioma initiation." (PMID 35402226, 2022). "To determine whether F11R expression was associated with increasing glioma malignancy grade, we first confirmed the differential protein expression of F11R in histological sections of human bone marrow and brain (p=0.0016)." (PMID 24147027, 2013). "In conclusion, HOXC-AS3 facilitates glioma growth through regulating miR-216 and F11R expression in vivo." (PMID 35402226, 2022). "F11R is overexpressed in glioma and positively related to the grade of glioma, and similar results were obtained in the NHAs and glioma cell lines." (PMID 35402226, 2022). "In this study, we discovered that the expression of F11R increased with the grade of glioma and that F11R promoted malignant progression downstream of miR-216." (PMID 35402226, 2022). "Current research suggests that HOXC-AS3 targets miR-216 as a sponge and that miR-216 regulates glioma progression by acting on F11R." (PMID 35402226, 2022). "To establish the clinical relevance of F11R to human GBM, we show that F11R expression correlates positively with glioma malignancy grade as well as correlates negatively with patient survival independent of GBM molecular subtype." (PMID 24147027, 2013). "In contrast to our prior findings with CD68 and IBA1, we found a positive correlation between the percent of F11R+ cells and high-grade glioma (p<0.0001)." (PMID 24147027, 2013). "Second, we quantified the percent of F11R+ cells (both resident and infiltrating macrophages) in a series of glioma tissue microarrays containing all glioma malignancy grades." (PMID 24147027, 2013). "In contrast, we now show that the percentage of F11R+ macrophages are increased in high-grade relative to low-grade glioma and that F11R tumor expression is an independent predictor of patient outcome, regardless of GBM molecular subtype." (PMID 24147027, 2013). "Collectively, these results reveal that the HOXC-AS3/miR-216/F11R signaling pathway is involved in the biological behavior of glioma and may serve as a novel potential target for the treatment of glioma." (PMID 35402226, 2022). "In conclusion, HOXC-AS3 facilitates glioma progression via miR-216 to regulate F11R." (PMID 35402226, 2022). "In summary, our study shows that the HOXC-AS3/miR-216/F11R axis plays an important role in the malignant progression of glioma, and may provide new ideas for the treatment of glioma." (PMID 35402226, 2022). "Furthermore, we disclosed that HOXC-AS3 modulates F11 receptor (F11R) expression by sponging miR-216 and facilitating glioma cell proliferation, migration, invasion, and tumor growth in vivo." (PMID 35402226, 2022). "Moreover, mononuclear cell F11R expression positively correlates with human high-grade glioma and additionally serves as a biomarker for GBM patient survival, regardless of GBM molecular subtype." (PMID 24147027, 2013). "Because the percent of F11R+ cells was greatest in the high-grade gliomas, we next asked whether F11R expression had prognostic value in predicting patient survival." (PMID 24147027, 2013). "Hence, we deduce that miR-216 inhibits glioma progression by regulating F11R expression." (PMID 35402226, 2022). "Hence, the HOXC-AS3/miR-216/F11R signaling pathway may provide a potential target for the treatment of glioma." (PMID 35402226, 2022). "We searched the expression level of candidate genes by GEPIA and found that only five genes (F11R, YBX1, BCAT1, IMPAD1, and RP2) were significantly upregulated in gliomas." (PMID 35402226, 2022). "Collectively, these data strongly suggest that F11r is a marker of brain macrophages in the context of murine GBM, regardless of tissue origin, prompting us to examine its prognostic value in patients with high-grade glioma." (PMID 24147027, 2013).
gastric cancer (8 papers, 2016 to 2023). A primary or metastatic malignant neoplasm involving the stomach. "Conclusively, F11R/JAM-A plays an essential role in gastric cancer progression through suppressed apoptosis and enhanced proliferation of cancer cells." (PMID 34533648, 2022). "The multipronged analysis showed F11R/JAM-A underexpression as a prognostic factor predicting poor clinical outcomes and enhanced tumor aggressiveness in gastric cancer patients." (PMID 34533648, 2022). "Low F11R/JAM-A expression level in gastric cancer promotes tumor cell invasion and migration, but not proliferation, and contributes to large tumor size, lymphatic vessel invasion, lymph node metastasis, and advanced TNM Classification of Malignant Tumors stage." (PMID 34533648, 2022).
Hypertension (7 papers, 2012 to 2024). The presence of chronic increased pressure in the systemic arterial system. "We also see three genes implicated in hypertension: Wisp1, Gna14, and F11r." (PMID 22471599, 2012). "Some researchers also verified that elevated levels of F11R in the circulation of patients were correlated with the severity of CAD and hypertension, which revealed the significant role of F11R in cardiovascular disease." (PMID 32714363, 2020).
melanoma (7 papers, 2012 to 2022). A malignant, usually aggressive tumor composed of atypical, neoplastic melanocytes. "To date, the F11R/JAM-A expression level in normal versus melanoma tissues is still undefined." (PMID 34533648, 2022).
head and neck squamous cell carcinoma (6 papers, 2016 to 2024). A squamous cell carcinoma that arises from any of the following anatomic sites: lip and oral cavity, nasal cavity, paranasal sinuses, pharynx, larynx, and salivary glands. "In head and neck squamous cell carcinoma (HNSCC), the F11R/JAM-A overexpression was revealed." (PMID 34533648, 2022).
non-small cell lung carcinoma (6 papers, 2013 to 2022). A group of at least three distinct histological types of lung cancer, including non-small cell squamous cell carcinoma, adenocarcinoma, and large cell carcinoma. "In patients with non-small cell lung cancer (NSCLC), F11R/JAM-A is mainly expressed in cell membranes." (PMID 34533648, 2022).
anaplastic thyroid carcinoma (4 papers, 2020 to 2025). "In anaplastic thyroid carcinoma (ATC) versus tissues from papillary thyroid cancer and normal thyroid, F11R/JAM-A underexpression was proved by the EMT-PCR array of 84 EMT-related genes." (PMID 34533648, 2022).
colorectal cancer (4 papers, 2021 to 2025). A primary or metastatic malignant neoplasm that affects the colon or rectum. "Recent research of the involvement of F11R/JAM-A and LFA-1 genetic variants in colorectal cancer development and metastasis was the first investigation of these gene variations in patients." (PMID 34533648, 2022).
coronary artery disease (4 papers, 2015 to 2025). "A prominent role for F11R in several inflammatory pathologic processes, including skin inflammation, meningitis, peritonitis, liver and myocardial ischemia, and coronary artery disease, has been recently recognized." (PMID 26114549, 2015).
endometrial carcinoma (4 papers, 2013 to 2022). A malignant tumor arising from the epithelium that lines the cavity of the uterine body. "F11R/JAM-A underexpression in high-grade and advanced endometrial cancers is associated with invasiveness and low overall patient survival and progression-free survival rates." (PMID 34533648, 2022). "In human endometrial carcinoma, the F11R/JAM-A expression is negatively correlated with poor patient prognosis (histologic grade, myometrial invasion, and stage)." (PMID 34533648, 2022). "Furthermore, in studies on 3D-cultured endometrial carcinoma cells, the reduced F11R/JAM-A expression in poorly differentiated (KLE cell line) versus well-differentiated adenocarcinoma (Ishikawa cell line) was confirmed." (PMID 34533648, 2022). "Further, we observed overexpression of an additional three genes in 8 of the 9 endometrial cancer cell lines: OCLN (occludin), F11R (JAM-A) and TJP3 (ZO-3)." (PMID 36484008, 2022). "Specifically, we have confirmed the role of deregulated CLDN and OCLN genes (which encode integral membrane proteins) and provided strong additional evidence for deregulated F11R (JAM-A) and TJP3 (ZO-3) in the development of endometrial cancer." (PMID 36484008, 2022).
endothelial dysfunction (3 papers, 2016 to 2025). In vascular diseases, endothelial dysfunction is a systemic pathological state of the endothelium (the inner lining of blood vessels) and can be broadly defined as an imbalance between vasodilating and vasoconstricting substances produced by (or acting on) the endothelium. "F11R (JAM-A), which regulates tight junctions and platelet adhesion, has been linked to endothelial dysfunction and thrombosis in SCAD cohorts." (PMID 40815415, 2025).
Hydrocephalus (3 papers, 2012 to 2020). Hydrocephalus is an active distension of the ventricular system of the brain resulting from inadequate passage of CSF from its point of production within the cerebral ventricles to its point of absorption into the systemic circulation. "Although some variation and severity were observed, knockdown of the corresponding six genes (BMPR2A, BMPR2B, TFRC, F11R, PTPRS, and PGRMC2) resulted predominantly in ciliopathic disorders, including abnormal development, hydrocephalus, kidney cysts, and left–right asymmetry in cardiac looping." (PMID 32832346, 2020).
ischemia (3 papers, 2014 to 2021). A hypoperfusion of the BLOOD through an organ or tissue caused by a PATHOLOGIC CONSTRICTION or obstruction of its BLOOD VESSELS, or an absence of BLOOD CIRCULATION. "Interestingly, the expression of CD321/JAM-A/F11R, one of essential molecules for transmigration of circulating leukocytes into inflammatory tissues, was significantly augmented on hepatic sinusoid endothelium at 1 h after ischemia and maintained until 45 min after reperfusion." (PMID 33737554, 2021).
thyroid cancer (3 papers, 2022 to 2025).
triple-negative breast carcinoma (3 papers, 2021 to 2023). An invasive breast carcinoma which is negative for expression of estrogen receptor (ER), progesterone receptor (PR), and human epidermal growth factor receptor 2 (HER2). "Similarly, in triple-negative breast cancer (TNBC) cells, F11R/JAM-A is significant in CSC self-renewal." (PMID 34533648, 2022).
cervical adenocarcinoma (2 papers, 2022 to 2024). An adenocarcinoma arising from the cervical epithelium. "The expression of F11R/JAM-A and claudin-1, 4, 7 proteins is significantly upregulated in patients with cervical adenocarcinoma and adenocarcinoma in situ (AIS)." (PMID 34533648, 2022).
cholestasis (2 papers, 2021). Impairment of the bile flow caused by obstruction within the liver, or outside the liver in the bile duct system. "By sequencing and bioinformatics analysis, CYP4A1, HACL1, F11R, and DBI were identified as possible pharmacodynamic gene targets of SHCZF in treating cholestasis rats." (PMID 34512777, 2021).
ciliopathy (2 papers, 2020 to 2023). A genetic disorder of the cellular cilia or the cilia anchoring structures, the basal bodies, or of ciliary function. "WES revealed biallelic variation in 3 ciliopathy genes (PKHD1, TMEM67 and IFT172) in 4 clinically unrelated index subjects (3 children and 1 adult), heterozygosity for a known variant in PPOX in one adult index subject, and homozygosity for an unreported splice-site variation in F11R in one child." (PMID 37471416, 2023). "The regulation of TMEM216 expression by F11R and PGRMC2 may partially explain the ciliopathy phenotypes seen in zebrafish model." (PMID 32832346, 2020).
COVID-19 (2 papers, 2022 to 2023). A disease caused by infection with severe acute respiratory syndrome coronavirus 2. "The UMAPs of AQP4, F11R, and SCUBE2 demonstrate the cell type-specific distribution of these proteins, but with no significant change under the COVID-19 condition when compared to the control group." (PMID 37239234, 2023).
Crohn disease (2 papers, 2017 to 2022). A gastrointestinal disorder characterized by chronic inflammation involving all layers of the intestinal wall, noncaseating granulomas affecting the intestinal wall and regional lymph nodes, and transmural fibrosis. "Allelic associations between TJ-related genes (F11R, MAGI1, MAGI2, MAGI3, PARD3, PTEN, and TJP1) and IBD, Crohn’s disease (CD), or ulcerative colitis (UC) were investigated." (PMID 28545409, 2017).
diffuse large B-cell lymphoma (2 papers, 2017 to 2022). "In diffuse large B-cell lymphoma patients with multiple extranodal lesions, F11R/JAM-A overexpression relation to EMT and cancer cell invasion in vitro and also in vivo were indicated." (PMID 34533648, 2022).
liver disease (2 papers, 2021 to 2023). "Whereas phenotypes of the index patients with mutated PKHD1, TMEM67, and PPOX corresponded with those elsewhere reported, how F11R variation underlies liver disease remains unclear." (PMID 37471416, 2023). "Recently, it has been discovered that F11R is related to some liver diseases." (PMID 34512777, 2021).
lung adenocarcinoma (2 papers, 2020 to 2022). A carcinoma that arises from the lung and is characterized by the presence of malignant glandular epithelial cells. "F11R/JAM-A upregulation was also observed in lung adenocarcinoma and atypical adenomatous hyperplasia of lung." (PMID 34533648, 2022).
microscopic colitis (2 papers, 2021 to 2025). Inflammation of the colon that is only apparent by microscopic examination. "F11R is a new candidate gene related to microscopic colitis (MC)." (PMID 34512777, 2021).
peripheral vascular disease (2 papers, 2020 to 2022). Any disorder affecting blood flow through the veins or arteries outside of the heart. "Considering the intense inflammatory response induced by Aβ, it is expected that the upregulation of JAM-A (F11r) and ESAM is associated with leukocyte transmigration in CAA vasculopathy." (PMID 35813502, 2022). "A recent report revealed that the mRNA and protein levels of F11R/JAM-A were increased in the atherosclerotic plaques of patients with advanced aortic and peripheral vascular disease." (PMID 32714363, 2020).
preeclampsia (2 papers, 2024 to 2025). Preeclampsia is a hypertensive disorder of pregnancy that is characterized by new-onset hypertension with proteinuria presenting after 20 weeks of gestation, and depending on mild or severe forms may initially present with severe headache, visual disturbances, and hyperreflexia. "Notably, the F11R, NOTCH1, GRHL3, and CLDN14 genes were associated with preeclampsia-associated PTB." (PMID 40625359, 2025). "Furthermore, previous findings indicated that F11R is one of the candidate genes for preeclampsia." (PMID 40625359, 2025).
renal cell carcinoma (2 papers, 2022). "In 282 biopsies from renal cell carcinoma (RCC) patients, the F11R/JAM-A underexpression and enhanced cancer cell migration were demonstrated, which means that this protein contributed to RCC progression." (PMID 34533648, 2022).